EGFR (epidermal growth factor receptor)
Diseases named in the same sentence as EGFR in open-access papers (continued):
Sharing a sentence is not in itself a finding about the gene and the disease.
lung cancer (continued). "The fact that both clonality and actionability of EGFR in the young lung cancer group were higher than those in the old lung cancer group, and the covalent chromatin modification pathway enriched in the young lung cancer group implied the multiple choices of young lung cancer treatment." (PMID 35096611, 2021). "Thus, there might exist an opposite effect between EGFR mutations and AC079630.4 expression on the regulation of TRAIL in lung cancer." (PMID 34282054, 2021). "Moreover, given that kinase inhibitors usually show milder toxicity than cytotoxic chemotherapy, the current Japanese Lung Cancer Society guideline for stage IV NSCLC recommends (level 1C) the use of any EGFR-TKI for the first-line treatment of elderly patients with a driver oncogene." (PMID 33648453, 2021). "However, some patients with EGFR-mutated lung cancer would be strongly associated with non-intrinsic factors, including SNPs." (PMID 33707471, 2021). "The research and wide application of EGFR-TKI (Tyrosine kinase inhibitors) drugs, mainly including Gefitinib, Erlotinib, Icotinib, Afatinib, Dasatinib, and Osimertinib, have greatly improved the overall survival of patients with lung cancer with the EGFR gene mutation." (PMID 34484285, 2021). "Our data suggest that single EGFR or MET inhibition might not be a good therapeutic option for EGFR-mutated lung cancer with MET amplification, and that inhibition of both pathways should be the best clinical choice in these patients." (PMID 34298655, 2021). "Therefore, the identified expression signature for TRM-like cells by itself can be used as a biomarker to stratify patients with lung cancer for anti-PD-1 immunotherapy regardless of their EGFR mutation status." (PMID 34663810, 2021). "However, no survival difference was found between high and low TMB/MATH score in the whole lung cancer patients without EGFR or ALK mutations receiving first-line chemotherapy." (PMID 34604048, 2021). "The association between osimertinib therapy and EphB4 also demonstrates that osimertinib decreased the expression of EphB4 and that the knockdown of EphB4 reduced the sensitivity of osimertinib in lung carcinoma cell lines regardless of the EGFR mutation status." (PMID 34445227, 2021). "Therefore, the current retrospective study was carried out to determine whether the decreased platelet count among lung cancer patients predicted the efficacy of EGFR-TKI treatment." (PMID 33243184, 2020). "The next‐generation sequencing (NGS) method was used to detect eight genes (EGFR, ALK, KRAS, ROS‐1, BRAF, ERBB2, RET, and c‐MET) and statistical analysis was used to determine which genes were the driving factors for brain metastasis associated with lung cancer." (PMID 31769228, 2020). "However, data on the pathology, AJCC TNM stage of lung cancer, BM, EGFR mutation status, and PS were not available in that study." (PMID 32917914, 2020). "Furthermore, recent studies supported Sharma and colleagues’ findings in the same lung cancer model and further showed that when DTPs were exposed to EGFR inhibitors for an extended period of time, they developed permanent resistance-conferring genetic mutations." (PMID 33213500, 2020). "Since EGFR mutations are reasonably specific for NSCLC, with frequencies as high as 58% in Asian patients with lung adenocarcinoma, it is rational to treat patients based on the detection of EGFR mutations in the setting of clinically suspected advanced lung cancer without pathologic diagnosis." (PMID 31991049, 2020).
lung cancer (continued). "However, since no EGFR mutations accounts for the majority of the lung cancer, the most appropriate treatment modality for resected lung cancer with no mutations is needed to be investigated." (PMID 32093621, 2020). "However, the prognostic role of combining clinical factor and radiomics of 18F-FDG PET in EGFR-mutated lung cancer has not been thoroughly studied." (PMID 33370365, 2020). "Therefore, blocking the overexpression of EGFR will inhibit the growth of lung cancer." (PMID 33292235, 2020). "To further confirm whether EGFR-TKI treatment affects CEA expression and metastasis in patients, we divided EGFR-mutant lung cancer patients into four groups based on their CEAIn (CEAIn < 5 ng/mL or CEAIn ≥ 5 ng/mL) and CEAPd levels (CEAPd < 5 ng/mL or CEAPd ≥ 5 ng/mL)." (PMID 32034239, 2020). "Furthermore, both CRISPR-Cas12a system and ddPCR did not produce positive results in the plasma samples of 24 lung cancer patients whose tumor tissues were negative for the EGFR mutations." (PMID 32093010, 2020). "Therefore, targeting PAK1 using PAK1 inhibitors might be a potential therapeutic strategy for treating EGFR-mutant lung cancer, especially among male smokers." (PMID 33261184, 2020). "Another study showed that all lung cancer-derived exosomes, regardless of the cancer type (EGFR-mutated adenocarcinoma, wild-type adenocarcinoma, squamous cell lung cancer), induced an increase of the matrix metalloproteinase 2 (MMP2) activity in cells exposed to TEXs." (PMID 32825667, 2020). "Through genetic testing, we identified a high prevalence of driver gene mutations in all CMPTs by whole exon sequencing, and we also found a non-frame shift insertion mutation in exon 20 of EGFR in the tumor tissues, which has been considered to be a key driving gene for lung cancer." (PMID 33133167, 2020). "In addition, data regarding types of chemotherapy received by the patients, and clinically important molecular profiling of lung cancer data on epidermal growth factor receptor (EGFR), anaplastic lymphoma kinase (AKA), and programmed death-1 (PD-1) were also not captured." (PMID 33718108, 2020). "Several studies demonstrated co-inhibition of both EZH2 and EGFR could show a synergic effect on tumor growth inhibition through inducing autophagy and increasing apoptosis in colon cancer cells, gastric cancer cells, and lung cancer cells." (PMID 32723346, 2020). "In lung cancer cell lines with either wild-type or mutant EGFR, treatment with erlotinib and gefitinib induced autophagy, and the degree of induction was greater in resistant cells, suggesting that autophagy is involved in both innate and acquired resistance to EGFR-target therapy." (PMID 33299639, 2020). "Current evidence has strongly suggested that ethnicity might be a risk factor for EGFR-mutant lung cancer, but there is no direct evidence from an admixed population." (PMID 32511065, 2020). "Therefore, the EGFR gene mutation caused problems in 40.9% of 552 patients with advanced NSCLC and EGFR could be considered as a main driven gene in these lung cancer patients." (PMID 31769228, 2020). "Interestingly, patients with mutation-driven cancer, such as EGFR-mutated lung cancer, derive nearly no benefit from immune checkpoint inhibition." (PMID 32085544, 2020). "To demonstrate how IDACombo can be used to identify candidate combinations of more than two drugs, we performed an analysis aimed at identifying drugs that could be added to the combination of cisplatin + gemcitabine to increase the treatment’s efficacy in EGFR wild type lung cancer." (PMID 33203866, 2020).
lung cancer (continued). "The exon 19 canonical deletion is one of the most common activating mutations in the never smoker lung cancer population, accounting for up to an estimated 25–30% of all EGFR activating mutations in lung cancer and approximately 60% of all exon 19 deletion damage in lung cancer." (PMID 31940362, 2020). "Together with findings that osimertinib increased the IGF-1R protein level, these results strongly suggest that an increased amount of IGF-1R, which maintains the association with EGFR and Gab1, may restore survival signals in AXL-low-expressing EGFR-mutated lung cancer cells exposed to osimertinib." (PMID 32929081, 2020). "Therefore, targeting EGFR is a strategy to inhibit the growth of lung cancer." (PMID 33292235, 2020). "Although somatic mutations in EGFR are more common among patients from East Asia, the prevalence of germline mutations in lung cancer cases in Japan was lower than that in North America, and, to our knowledge, no case of germline T790M EGFR mutation in East Asia has been reported in the literature." (PMID 32104210, 2020). "We did not evaluate the synergistic effect of KPT-185 as it already had a very strong inhibitory effect on PC9GR cells; however, its combination with other drugs might even be more effective in the treatment of EGFR-TKI-resistant lung cancer, which is one of our future plans." (PMID 32923394, 2020). "In addition, at the moment of the study, Epidermal growth factor receptor and anaplastic lymphoma kinase, the most commonly mutated oncogenes that involve the pathogenesis of lung cancer, were not accessible in Cuba." (PMID 32807114, 2020). "Therefore, in-depth study of the mechanism of drug resistance to EGFR-TKIs, the search for genes related to drug resistance, and the exploration of ways to reverse drug resistance have recently become important topics in lung cancer treatment research." (PMID 33056982, 2020). "However, this experiment does not reflect the actual clinical situation, because EGFR-TKIs are usually prescribed to patients with EGFR mutation, and most EGFR-mutated lung cancers are adenocarcinomas." (PMID 32552717, 2020). "Furthermore, in lung cancer cells, localization of EGFR onto mitochondria and its interaction with subunits of OXPHOS Complex IV have been characterized, although their function remains unknown." (PMID 32210009, 2020). "So, FGL2 might affect EGFR by influencing immune status in tumor environment of lung cancer." (PMID 32206449, 2020). "On the other hand, in China, the same group of 5 oncogenes amounted to 81% of lung cancers, which is largely attributable to the high frequency of EGFR mutations including multiple occurrences of the EGFR mutations as seen in China, vs. to non-Asian populations." (PMID 32850378, 2020). "Moreover, because AURKA can enhance the resistance of lung cancer to third-generation EGFR inhibitors, a dual effect of AURKA SNPs and EGFR mutations on the clinicopathological characteristics of LADC may occur, thus requiring evaluation." (PMID 33050100, 2020). "The activated cell-membrane α7nAChRs formed complexes with EGFR, whereas activated mitochondrial α7nAChRs was physically associated with the intramitochondrial protein kinases PI3K and Src that increased expression of cyclin D1 and activation of ERK1/2 lead to lung cancer proliferation." (PMID 31956359, 2020). "However, the EGFR-sensitizing mutations observed in lung cancers are very uncommon in HNSCC, and there are currently no predictive markers for erlotinib response in clinical use." (PMID 32929368, 2020). "Besides 19del and L858R, EGFR amplification is also frequently occurs in lung cancer." (PMID 33219256, 2020). "On the other hand, amplification of MDM2 and EGFR mutations is related to hyperprogression among patients with advanced solid cancers during ICB treatment, and PD‐1 blockade could trigger immune escape in lung cancers driven by EGFR, as shown in preclinical studies." (PMID 32997401, 2020).
lung cancer (continued). "However, efficient molecular testing techniques to detect common gene mutations in EGFR using LBC specimens from the sputum of patients with lung cancer, have not yet been proposed." (PMID 32033355, 2020). "The presence of the mutated epidermal growth factor receptor (EGFR) alleles in exoDNA, especially mutations such as exon 19 Del and exon 21 L858R, characteristic of lung cancer cells, may be important when selecting patients for targeted therapy using a tyrosine kinase inhibitor." (PMID 32537468, 2020). "Finally, we used EGFR-mutant lung adenocarcinoma cells to monitor the change of CEA heterogeneity after EGFR-TKI treatment and its association with dissemination and chemoresistant properties of lung cancer cells." (PMID 32034239, 2020). "Moreover, there is a relatively high percentage of AYAs with lung cancer who never smoked and have driver mutations, such as EGFR, ALK, KRAS, and ROS1." (PMID 33218178, 2020). "Brain metastasis of epidermal growth factor receptor (EGFR) sensitive mutations is a hot and difficult point in targeted era of non-small cell lung cancer (NSCLC) treatment, meanwhile it is also the central issue of controversy in the field of lung cancer treatment." (PMID 32746605, 2020). "First, this haplotype was correlated to an EGFR mutated status supporting the rationale that both SNPs by itself could participate in the development of lung cancer with non-smoking history." (PMID 33324556, 2020). "For locally advanced lung cancer, there are no prospective studies that have assessed whether individuals with EGFR-activating mutations could benefit from targeted therapy as the first-line treatment." (PMID 32563259, 2020). "A positive association between the TT genotype SNP rs4886578 and rs736118, individually and in the haplotype form, was observed with non-smoking history and EGFR mutational status; suggesting its involvement in the genesis of lung cancer unrelated to tobacco exposure." (PMID 33324556, 2020). "In this study, we prospectively explored the role of ctDNA in detecting EGFR mutations in patients' plasma and determined the efficacy of EGFR tyrosine kinase inhibitors (TKIs) in patients with suspected advanced lung cancer, in the absence of pathologic diagnosis." (PMID 31991049, 2020). "However, the regulatory mechanisms of PD-L1 and the activity of immune checkpoint inhibitors in EGFR-TKI resistant lung cancer remain unclear." (PMID 31747941, 2019). "GK5 could be a potential target for treating patients with EGFR-TKI-resistant lung cancer." (PMID 30791926, 2019). "Interestingly, LCAT1 was upregulated in a distinct subgroup of lung cancer patients who did not have actionable mutations in EGFR, ALK, ROS or NRAS." (PMID 31779616, 2019). "EGFR G796/C797, L792 and L718/G719 mutations, MET and HER2 amplification, BRAF, KRAS, and PIK3CA mutations, oncogenic fusion mutations in FGFR3, RET, and NTRK were recently identified in a large cohorts of osimertinib-resistant lung cancer patients either treated in second-line and in first-line." (PMID 31138260, 2019). "Finally, by correlating the status of AK4 mRNA expression with drug sensitivity data in lung adenocarcinoma cell lines, we proposed lung cancer cells that have high levels of AK4 might be sensitive to EGFR target therapy." (PMID 31444368, 2019). "As COPD is a well-known smoking-related disease, the incidence of an EGFR mutation in COPD patients with lung cancer might be lower than in non-COPD patients." (PMID 31336878, 2019). "EGFR-positive lung cancer cell lines, including HCC827, A549, and H1975, were individually treated with a panel containing 172 therapeutic agents targeting stem cell-associated genes to search for potential agents that could be applied against EGFR-positive lung cancers." (PMID 31619200, 2019).
lung cancer (continued). "Besides EGFR mutational status, both ALK rearrangements and point mutations linked to resistance to tyrosine kinase inhibitors were successfully evaluated in plasmatic cfDNA of lung cancer patients." (PMID 31861557, 2019). "In addition to KRAS and EGFR T790 mutations, the expression of oncogenes, including MET, HER2 (ERBB2), and epidermal growth factor receptor 3 (HER3, ERBB3), is associated with drug resistance against EGFR-TKIs and leads to tumor recurrence in lung cancers." (PMID 31619200, 2019). "Single nucleotide mutations, including polymorphisms of epidermal growth factor receptor (EGFR), KRAS proto-oncogene, GTPase (KRAS), and rearrangements of the ALK receptor tyrosine kinase (ALK) gene, are also involved in the occurrence of low-grade metastatic adenocarcinoma-type lung cancer." (PMID 31245210, 2019). "However, it requires further study to determine whether modulation of AK4 and/or AK1 may overcome T790M-mediated resistance, and through what mechanisms adenylate kinases isoform network may modulate EGFR signaling turn over in lung cancer." (PMID 31444368, 2019). "DLC3 knockdown prevented EGFR degradation and enhanced Akt activation by trapping the receptor in EEA1-positive endosomes, making it tempting to speculate that reduced DLC3 expression might also confer EGFR-TKI resistance as described for lung cancers overexpressing RhoB." (PMID 31766364, 2019). "We speculate that EGFR activation, in addition to NRF2 activating mutation or Keap1 dysfunction, might represent a complimentary mechanism for upregulating the serine biosynthetic pathway via NRF2-ATF4 axis in lung cancer." (PMID 31221965, 2019). "Therefore, STAT3 activation induced by LDOC1 silencing may be associated with genetic abnormalities of EGFR and ALK and may exert a synergistic effect in lung cancer; this topic may be worth exploring in the future." (PMID 30634502, 2019). "Then, WFA and glucose transport inhibitor (phloretin) treatment was introduced causing a dramatic reduction in tumor size, suggesting that the combination of WFA and metabolism targeting therapies could be an effective therapeutic strategy against EGFR resistant lung cancer." (PMID 31731424, 2019). "To improve the cytotoxicity of ibrutinib towards lung cancer, we synthesized a series of ibrutinib derivatives, of which Ibr‐7 exhibited superior anti‐cancer activity to ibrutinib, especially against epithelial growth factor receptor (EGFR) wild‐type NSCLC cell lines." (PMID 30663221, 2019). "However, lung cancer patients without EGFR mutation who receive gefitinib show shorter progression-free survival compared with patients treated with platinum-based chemotherapy." (PMID 30956990, 2019). "Furthermore, TKIs increase PM localization of EGFR in lung cancers and PDGFRA/KIT in GISTs." (PMID 31484543, 2019). "Taken together, our findings suggest that more work is needed to evaluate the nature of rare EGFR variants in lung cancer and that JAKis may represent a new strategy to inhibit rare variants of EGFR that do not respond to EGFR‐targeted TKIs." (PMID 31314158, 2019). "Therefore, WA alone or in combination with standard chemotherapy is a potential treatment option for EGFR wild-type lung cancer and may decrease the occurrence of cisplatin resistance by inhibiting lung CSCs." (PMID 31319622, 2019). "Therefore, EGFR-tyrosine kinase inhibitors (TKIs), such as gefitinib, afatinib, and osimertinib, specifically targeting EGFR wild-type (WT), EGFR and HER2 dual targets, and EGFR T790 M, respectively, are effective therapeutic agents for the eradication of lung cancers." (PMID 31619200, 2019). "However, whether miR‐206 may overcome IL6‐induced gefitinib resistance in EGFR‐mutant lung cancer remains elusive." (PMID 31507089, 2019).